ARG2 (arginase 2)
Diseases named in the same sentence as ARG2 in open-access papers (continued):
Sharing a sentence is not in itself a finding about the gene and the disease.
renal cell carcinoma (3 papers, 2008 to 2024). "Germline whole-body Arg2 deficiency also induces spontaneous steatohepatitis and promotes renal cell carcinoma progression, and activating Arg2 promotes T cell energetics and fitness." (PMID 38280549, 2024).
thyroid tumor (3 papers, 2022 to 2024). A benign or malignant neoplasm affecting the thyroid gland. "In the most malignant thyroid tumors, ARG2 expression was increased compared to healthy tissues, and silencing the Arg2 gene decreased AKT expression, causing apoptosis and reducing the expression of cell proliferation." (PMID 39337272, 2024). "ARG2 expression is markedly greater in malignant thyroid tumours than in normal tissues, and the suppression of ARG2 decreases AKT expression while increasing tumour cell apoptosis." (PMID 39051546, 2024).
allergic asthma (2 papers, 2017 to 2022). A asthma with a basis in a pathological type I hypersensitivity reaction. "CpG promoter loci of allergic asthma genes (e.g., interleukin 4 (IL4), interferon gamma (IFNγ), inducible nitric oxide synthase (NOS2A)), arginase 2 (ARG2)) were pyrosequenced at the start and end of each sampling period." (PMID 28588744, 2017).
anemia (2 papers, 2021 to 2024). A reduction in the number of red blood cells, the amount of hemoglobin, and/or the volume of packed red blood cells. "We found that in adult mice anemia induced the expansion of early-stage CECs that had the highest expression of ARG2." (PMID 34893694, 2021). "Here, we show that in mice early-stage CECs expand in anemia, have high levels of arginase 2 (ARG2) and reactive oxygen species (ROS)." (PMID 34893694, 2021). "In patients with anemia, CECs expand in the peripheral blood and express ARG1 and ARG2, which suppress IFN-γ production by T cells." (PMID 39474425, 2024). "In humans with anemia, CECs expand and express ARG1 and ARG2 that suppress T-cells IFN-γ production." (PMID 34893694, 2021). "In mice with anemia, CD45+ CECs expand in the spleen and express high levels of ARG2 and ROS." (PMID 39474425, 2024).
brain tumour (2 papers, 2017 to 2022). "Here we show in large in silico patient cohorts that paediatric sarcomas and brain tumours express predominately the arginine transporter SLC7A1 and the arginine metabolising enzyme Arginase 2 (ARG2), but have low-absent expression of OTC." (PMID 28969007, 2017).
childhood asthma (2 papers, 2011 to 2021). "In a childhood asthma study done among 433 case‐parent triads, genetic variation in ARG2 had an increased risk of childhood asthma." (PMID 34800009, 2021).
colorectal cancer (2 papers, 2021 to 2026). A primary or metastatic malignant neoplasm that affects the colon or rectum. "In addition, they revealed that the downregulation of ARG2 inhibits the growth of colorectal cancer cells." (PMID 33968341, 2021).
diabetic nephropathy (2 papers, 2024 to 2025). "The lack of Arg2 in these mice protected them against streptozotocin-induced albuminuria, macrophage recruitment, and histopathological changes, leading to renal tissue protection and thus suggesting a role of Arg2 in diabetic nephropathy." (PMID 39952693, 2025).
erectile dysfunction (2 papers, 2024). Persistent or recurrent inability to achieve or to maintain an erection during sexual activity. "Furthermore, CO hydrosol was evaluated against enzymes associated with erectile dysfunction, namely acetylcholinesterase (AChE), angiotensin-I converting enzyme (ACE), and arginase type 2 (ARG2)." (PMID 38891326, 2024). "Application: prospects for development of an additive or ingredient for natural remedy for erectile dysfunction;Extraction procedure: SD;Chemical composition: GC–MS;Biological characterisation: PDE5, ACE, AChE, and ARG2 inhibition assays." (PMID 39407589, 2024).
gastric adenocarcinoma (2 papers, 2004 to 2007). "Group 3 contained mainly gastric adenocarcinoma characterized by overexpression of arg2, a gene that has been reported to be overexpressed in many cancers including gastric adenocarcinoma." (PMID 19412438, 2007). "In group 3, which consisted mainly of gastric adenocarcinomas, only ARG2 exhibited a high level of expression." (PMID 14710232, 2004).
Granuloma (2 papers, 2015 to 2023). A compact, organized collection of mature mononuclear phagocytes, which may be but is not necessarily accompanied by accessory features such as necrosis. "arg2:GFP-positive granuloma-associated neutrophils represented 37.9% of neutrophils imaged around granulomas, with the remaining 62.1% having no detectable arg2:GFP expression." (PMID 37078586, 2023). "The granuloma-associated arg2:GFP expression observed may also be from epithelioid-like cells that make up a large proportion of the zebrafish Mm granuloma structure, some of which are macrophage derived but may have lost macrophage markers." (PMID 37078586, 2023). "In contrast with these results, we did not observe a significant decrease in M1 marker genes, including MMP9, NOS2, CCL2, IL-6 and ARG2, in granuloma FCMs compared with NFMs, although MMP13 and NF-κB1 levels, which are also M1-related genes, were decreased." (PMID 26197235, 2015). "The low number of mpeg:mCherry/arg2:GFP double-positive macrophages observed at 4 dpi, alongside arg2:GFP-positive neutrophils, did not appear to account for the many granuloma-associated arg2:GFP-positive cells that were observed, with many appearing to be mpeg:mCherry negative." (PMID 37078586, 2023).
Hyperammonemia (2 papers, 2018 to 2020). An increased concentration of ammonia in the blood. "We also know that knocking out Arg1 was lethal in mice due to hyperammonemia caused by arginase deficiency, whereas the Arg2 knockout mice had intact phenotypes and Arg1/Arg2 double knockout mice exhibited the same arginase deficiency phenotype as the Arg1 single knockout mice." (PMID 33519806, 2020).
kidney damage (2 papers, 2021 to 2026). "Studies have shown upregulation of renal Arg-2 protein expression in diabetic Akita mice, and treatment with the Arg-2 inhibitor effectively attenuates albuminuria and other markers of kidney damage." (PMID 41601953, 2026). "Arginase-2 (Arg-2) and transforming growth factor-beta 1 (TGF-β1) are two markers of kidney damage by renal IR." (PMID 34829595, 2021).
lung squamous cell carcinoma (2 papers, 2018 to 2019). "ARG2 was shown to be highly expressed in H520 squamous cell lung carcinoma (lung SCC) xenografts but undetectable in SK-MES-1 and SW900 lung SCC xenografts." (PMID 30808864, 2019). "CA4 and HMOX1 achieved the best AUC performance (AUC = 0.9 and AUC = 0.89) in liver hepatocellular carcinoma, LTC4S and NEUROD1 in lung adenocarcinoma (AUC = 0.998 and AUC = 0.994), FANCA and ARG2 in lung squamous cell carcinoma (AUC = 0.992 and AUC = 0.956)." (PMID 29304754, 2018).
lymphopenia (2 papers, 2023 to 2025). Reduction in the number of lymphocytes. "In the human context, we revealed that CXCR2Hi MDSC increased in peripheral in septic patients and correlated significantly to lymphopenia and elevated ARG2 levels." (PMID 40860137, 2025). "In conclusion, our research underscores the critical role of ARG2-enriched CXCR2Hi MDSCs in sepsis-induced lymphopenia and immunosuppression and highlights the p38-MAPK pathway as a central regulator of CXCR2Hi MDSCs." (PMID 40860137, 2025). "This research advances the understanding of PIS immunopathology and paves the way for developing precision therapies to modulate the ARG2-enriched CXCR2Hi MDSC to combat septic lymphopenia and immunosuppression." (PMID 40860137, 2025). "Our findings underscore the role of ARG2-enriched CXCR2Hi MDSCs in the pathogenesis of septic lymphopenia and propose ARG2 as a promising therapeutic target for immunomodulation in sepsis." (PMID 40860137, 2025). "Therefore, developing novel drugs or antibodies selectively targeting ARG2 offered an attractive immunotherapeutic method to prevent T-cell lymphopenia and improve the prognosis of critically ill patients." (PMID 40860137, 2025). "We have uncovered a critical subpopulation of MDSCs, ARG2-enriched CXCR2Hi MDSC, that are pivotal in the pathogenesis of septic lymphopenia." (PMID 40860137, 2025). "Our data revealed a negative correlation between ARG2-enriched CXCR2Hi MDSCs and lymphopenia, suggesting a potential role of these cells in septic lymphopenia." (PMID 40860137, 2025).
medulloblastoma (2 papers, 2017 to 2022). A malignant, invasive embryonal neoplasm arising from the cerebellum. "In medulloblastoma MYC (associated with a poor prognosis) had a positive correlation with FDR <0.05, for both the OTC and ARG2 oncogenic and hallmark gene lists." (PMID 28969007, 2017).
myocardial infarct (2 papers, 2016 to 2025). "In addition to functional recovery, triphenyl tetrazolium chloride (TTC) staining (myocardial infarction) upon I/R injury in males is significantly reduced in the age-matched male Arg2-/- animals." (PMID 41187268, 2025). "Finally, we demonstrate that Arg2-/- mice in aging exhibit improved cardiac function and are more resistant to ischemic/reperfusion stress and reveal a better recovery and less myocardial infarct area as compared to the old wt animals." (PMID 41187268, 2025).
non-small cell lung carcinoma (2 papers, 2021 to 2025). A group of at least three distinct histological types of lung cancer, including non-small cell squamous cell carcinoma, adenocarcinoma, and large cell carcinoma. "In the current study, we investigated the expression of ARG2 and ASS1 in non-small cell lung carcinomas." (PMID 34344457, 2021).
osteoarthritis (2 papers, 2020 to 2021). A noninflammatory degenerative joint disease occurring chiefly in older persons, characterized by degeneration of the articular cartilage, hypertrophy of bone at the margins and changes in the synovial membrane. "Recently, ARG2 was shown to cause destruction of osteoarthritis cartilage by upregulating the level of matrix metalloproteinases (MMPs) in chondrocytes." (PMID 34926442, 2021). "Previously, ARG2 has been reported to regulate osteoarthritis pathogenesis by regulating the levels of matrix degrading enzymes in chondrocytes." (PMID 34926442, 2021). "A recent study published in 2019 showed the detrimental role of Arg2 overexpression in the pathogenesis of osteoarthritis when it upregulated pro-inflammatory cytokines in osteoarthritis cartilage." (PMID 31979015, 2020). "For example, Arg2 overexpression has been demonstrated to contribute to the destruction of osteoarthritis cartilage and osteoarthritis pathogenesis." (PMID 31979015, 2020).
ovarian carcinoma (2 papers, 2018 to 2023). A malignant neoplasm originating from the surface ovarian epithelium. "PRMT5, PRMT1, DDAH1, DDAH2, NOS2, ARG1, and ARG2 were all found to be up-regulated in the stage I/II or stage III/IV ovarian cancer tissues compared to normal tissues." (PMID 37684587, 2023). "For example, ARG2 and MMP1 expression have been found to correlate with poor prognosis in gastric and ovarian cancer, respectively." (PMID 30416686, 2018). "Notably, gene clusters of PRMT1/PRMT5 and DDAH1/DDAH2/ARG2 persisted, while other gene tree relationships and expression significances differed between the two comparisons: normal tissue versus stage I/II ovarian cancer and stage I/II versus stage III/IV ovarian cancer." (PMID 37684587, 2023).
acute lymphoblastic leukemia (1 paper, 2018). Leukemia with an acute onset, characterized by the presence of lymphoblasts in the bone marrow and the peripheral blood. "Here, we confirmed the expression of ARG2 in a panel of hematologic malignancies [AML, acute lymphoblastic leukemia (ALL) cell lines and multiple myeloma (MM)]." (PMID 30307989, 2018).
adenoma (1 paper, 2009). A neoplasm arising from the epithelium. "Damage-inducible transcript 3 (DDIT3) and arginase II (ARG2) showed a high specificity with 85% positivity in carcinomas and only 9,4% positivity in adenomas." (PMID 19321014, 2009).
adenomyosis (1 paper, 2025). The growth of endometrial tissue inside the muscular wall of the uterine corpus. "Emerging studies have shown that ARG2 levels are elevated in patients with adenomyosis." (PMID 41278208, 2025). "Furthermore, emerging research has shown that the level of ARG2 is increased in adenomyosis, and ARG2 plays a role in adenomyosis by regulating the Wnt/β-catenin signaling pathway." (PMID 41278208, 2025).
Allergy (1 paper, 2019). An allergy is an immune response or reaction to substances that are usually not harmful. "The highest levels of arginase 2 were observed in the non-asthmatic sinusitis without allergy group (NASsA), according to Han’s subclassification." (PMID 31683763, 2019). "We also determined the differentiated expression of ARG2 in the subgroups of patients with CRS defined by Han and detected the highest levels in the non-asthmatic sinusitis without allergy subtype." (PMID 31683763, 2019).
Alzheimer disease (1 paper, 2025). A progressive, neurodegenerative disease characterized by loss of function and death of nerve cells in several areas of the brain leading to loss of cognitive function such as memory and language. "In recent decades, the abnormal expression of ARG-1 or ARG-2 has been reported to be increasingly linked to a variety of diseases, including cardiovascular disease, inflammatory bowel disease, Alzheimer’s disease, and cancer." (PMID 39861764, 2025).
autoimmune disease (1 paper, 2025). A disorder resulting from loss of function or tissue destruction of an organ or multiple organs, arising from humoral or cellular immune responses of the individual to their own tissue constituents. "ARG2 expression has also been associated with immune cell infiltration in inflammatory and autoimmune diseases, like steroid-induced osteonecrosis, supporting its broader immunomodulatory relevance." (PMID 40977888, 2025).
C. perfringens infection (1 paper, 2019). "C. perfringens infection significantly increased the mRNA expression of iNOS and arginase 2 (ARG2) (P < 0.05) in the jejunum of birds." (PMID 31428367, 2019). "In our study, C. perfringens infection increased jejunal mRNA expression of iNOS, ARG2 and ADC, as well as increasing iNOS activity in the jejunal mucosa, which stimulated arginine catabolism, leading to serum arginine deficiency." (PMID 31428367, 2019).
Cerebral ischemia (1 paper, 2022). Restriction of arterial blood supply to the brain associated with insufficient oxygenation to support the metabolic requirements of the tissue. "A study using Arg2-deficient mice showed larger infarct volume, worse excitotoxic injury, reduced cerebral blood flow, and neurological deficits after cerebral ischemia." (PMID 36361836, 2022).
chronic gastritis (1 paper, 2017). Inflammation of the stomach that is chronic in nature. "The reason why the usefulness of Arg2 inhibitors against GI cancer is arguable is epitomized by a study in which Arg2 deficiency exacerbated gastric immunopathology during chronic gastritis." (PMID 28191010, 2017).
chronic rhinosinusitis (1 paper, 2019). Chronic form of sinusitis. "In patients with chronic rhinosinusitis, significantly higher ARG2 values were observed compared to the control group (FR 2.22 ± 0.42 vs. 1.31 ± 0.21, p = 0.016)." (PMID 31683763, 2019). "Regarding ARG2, a significantly higher expression was found in the group of patients with chronic rhinosinusitis compared to the control group, sustaining its repercussion on sinusitis pathology." (PMID 31683763, 2019). "The levels of ARG2 were significantly higher in patients with chronic rhinosinusitis compared to the control group (fold regulation (FR) 2.22 ± 0.42 vs. 1.31 ± 0.21, p = 0.016)." (PMID 31683763, 2019). "Statistically significantly higher ARG2 levels were also identified in non-allergic, non-asthmatic patients with chronic rhinosinusitis compared to the control group (FR 2.75 ± 0.68 vs. 1.31 ± 0.21, p = 0.025)." (PMID 31683763, 2019). "In the other subgroups of patients with chronic rhinosinusitis (allergic asthmatic, non-allergic asthmatic, allergic non-asthmatic), no statistically significantly different ARG2 values were found (FR 1.15 ± 0.59, 2.05 ± 0.67, 1.03 ± 0.23) compared to the control group." (PMID 31683763, 2019).
clear cell renal cell carcinoma (1 paper, 2018). "In clear cell renal cell carcinoma, reduced ARG2 activity promotes tumor growth through conserving the critical biosynthetic cofactor pyridoxal phosphate and avoiding toxic polyamine accumulation, indicating tumor-restricting properties of ARG2." (PMID 30320132, 2018).
ependymoma (1 paper, 2017). A WHO grade II, slow growing tumor of children and young adults, usually located intraventricularly. "In ependymoma EGFR upregulation, a target of monoclonal antibodies and small molecule inhibitors, correlated with ARG2 (FDR 0.000)." (PMID 28969007, 2017).
fracture (1 paper, 2021). "The expression of ARG2 was also examined in nucleus pulposus tissues from patients with lumbar vertebral fracture or IDD." (PMID 34926442, 2021).
Fungal infections (1 paper, 2023). "Fungal infections have been shown to modulate host arginine metabolism via arginase; therefore, we assessed arg2:GFP expression in two well-characterised fungal zebrafish infection models – C. albicans and C. neoformans." (PMID 37078586, 2023). "In both fungal infections, arg2:GFP was observed in a subpopulation of lyz:mCherry-positive neutrophils at 1 dpi." (PMID 37078586, 2023). "Our findings using the arg2:GFP line are consistent with these mammalian observations, with early arginase expression observed in innate immune cells after Mm and fungal infection." (PMID 37078586, 2023).
Glucose intolerance (1 paper, 2019). Glucose intolerance (GI) can be defined as dysglycemia that comprises both prediabetes and diabetes. "Here we identify arginase 2 (Arg2) as a fasting-induced hepatocyte factor that protects against hepatic and peripheral fat accumulation, hepatic inflammatory responses, and insulin and glucose intolerance in obese murine models." (PMID 30962478, 2019).
HCMV infection (1 paper, 2022). "Similarly, hsa-miR-199a-3p and hsa-miR-613 were found downregulated in HCMV infection targeting AKT1 and ARG2 genes, respectively." (PMID 36159991, 2022).
HIV-1 infection (1 paper, 2019). The type species of lentivirus and the etiologic agent of acquired immunodeficiency syndrome (AIDS). "Thus, we hypothesized that arginase-2 activity by CECs may enhance HIV-1 infection/replication in CD4+ T cells." (PMID 31772057, 2019). "In contrast, we found that overriding the enzymatic activity of arginase-2 by l-arginine supplementation did not abrogate the enhanced HIV-1 infection in CD4+ T cells when cocultured with CECs." (PMID 31772057, 2019).
infarction (1 paper, 2025). A localised pathological necrosis of tissue resulting from obstruction of the blood supply usually by a thrombus, an embolus, or vascular torsion. "The absence of ARG2 in cardiomyocytes is also demonstrated in the heart of other species such as rats, in which no staining could be found in the cardiomyocytes (with or without infarction) but in non-cardiomyocytes that is cells between myocytes and endocardial cells." (PMID 41187268, 2025).
influenza infection (1 paper, 2018). "The ORNs-d-М injection for prevention and treatment of the influenza infection reduced the mRNA level of nos2, arg2, and xdh expression in comparison with the virus-infected mice." (PMID 30037133, 2018).
Mm (1 paper, 2023). "It is important to note that the mpeg promoter used to mark macrophages in our study is downregulated by Mm infection; therefore, it is possible that our observations using the mpeg:mCherry line is an underestimation of the population of macrophages that express arg2:GFP during Mm infection." (PMID 37078586, 2023).